NT5E (5'-nucleotidase ecto)
Diseases named in the same sentence as NT5E in open-access papers (continued):
Sharing a sentence is not in itself a finding about the gene and the disease.
hematological malignancies (6 papers, 2017 to 2024). "The gene expression of NT5E has been studied as a prognostic marker in many solid tumors and hematologic malignancies." (PMID 28481355, 2017).
bacterial infection (5 papers, 2015 to 2021). "NTPDase1/CD39 and NT5E/CD73 may also affect antibacterial response by modulating Treg activity, while NTPDase1/CD39 is upregulated on both CD4+ and CD8+ Teff cells at sites of acute inflammation thus attenuating responses to bacterial infections." (PMID 33613285, 2020).
genetic disease (5 papers, 2018 to 2025).
cardiovascular diseases (4 papers, 2021 to 2025). "Variants in the ENPP1, ABCC6 and 5'-nucleotidase ecto (NT5E) genes, which are involved in metabolism of PPi and Pi, have been found to predispose to coronary arterial, valvular calcification and other cardiovascular diseases." (PMID 35387434, 2022).
NT5E also shares sentences with these, for which no sentence is quoted: triple-negative breast carcinoma (37 papers); non-small cell lung carcinoma (33); breast tumor (23); colitis (20); leukemia (15); lung fibrosis (15); myocardial infarction (15); pancreatic ductal adenocarcinoma (15); lymph node metastasis (14); Sepsis (13); serous ovarian cancer (13); atherosclerosis (11); myeloma (11); viral infections (11); endometriosis (10); metastatic melanoma (10); metastatic tumors (9); ovarian tumor (9); prostate tumor (9); rheumatoid arthritis (9); adenocarcinoma (8); Arthritis (8); diabetes (8); endothelial dysfunction (8); experimental autoimmune encephalomyelitis (8); gallbladder cancer (8); inflammatory bowel disease (8); Pseudoxanthoma elasticum (8); sarcoma (8); bladder cancer (7).
A further 316 diseases each share a sentence with NT5E in 7 papers or fewer.